IL6 (interleukin 6)
Diseases named in the same sentence as IL6 in open-access papers (continued):
Sharing a sentence is not in itself a finding about the gene and the disease.
Insulin resistance (continued). "Conversely, when IKK2 is superactivated in fasting liver or neonatal liver, where IKK1 is low and FOXO1 activity is high, FOXO1 synergizes with p65/p50 to cause insulin resistance and induce proinflammatory IL-1β, IL-6, CCL2, and CCL20, resulting in progressive inflammation and/or liver fibrosis." (PMID 26219821, 2015). "Moderately increased IL-6 levels seen in obese individuals may contribute to the development of obesity-associated complications, e.g., insulin resistance, via the inhibition of lipoprotein lipase activity in the adipose tissue." (PMID 26516848, 2015). "Also, an increase in glycemic load occurred simultaneously with exacerbated levels of inflammatory biomarkers such as interleukin-6, linked to insulin resistance." (PMID 26225136, 2015). "Our study suggests that extracellular HCV core protein with substitution at position 70 enhanced IL-6 production and reduced adiponectin production from visceral adipose tissue, which can cause insulin resistance, hepatic steatosis, and ultimately development of HCC." (PMID 26121241, 2015). "In addition, there are associations among insulin resistance, abdominal obesity, and serum immune markers such as IL6 and TNFα." (PMID 26170888, 2015). "Insulin resistance is also an important risk factor for cardiovascular disease, as this results in increased secretion of proinflammatory cytokines, such as tumor necrosis factor-α and interleukin-6." (PMID 26618774, 2015). "Insulin resistance might be caused by pro-inflammatory cytokines, and we found that IL-6, TNF-α and IL-1β were up regulated in aged male GADD34-deficient mice." (PMID 26316333, 2015). "Interleukin-6 (IL-6) is a proinflammatory cytokine, which is produced by many cells (adipocytes, activated leucocytes, myocytes and endothelial cells) and is also associated with visceral obesity and insulin resistance." (PMID 26239462, 2015). "IL-6 and CRP may contribute to MS risk, and a sharp increase in FFA can cause both insulin resistance (IR) in the liver, increase the expression of proinflammatory cytokines such as IL-6, and stimulate the liver to secrete CRP." (PMID 26246695, 2015). "Between these cytokines, IL-6 is implicated to insulin resistance." (PMID 26635627, 2015). "CRP is associated with insulin resistance while IL-6 may interfere with insulin signalling through induction of proteins that bind to the insulin receptor." (PMID 25548896, 2014). "WC is strongly associated with sarcopenic obesity and insulin resistance, both of which are related to functional decline, frailty and disability, and thought to be partially mediated by an increase in pro-inflammatory markers, including IL-1, IL-6, and TNF-a." (PMID 25106459, 2014). "Also, have been shown that TNF-α and IL-6 cause systemic insulin resistance through activation of MAP kinases, protein kinase C (PKC) and SOCS-3 mediated proteasome degradation." (PMID 24966877, 2014). "Given that an ANP-mediated reduction of TNF-α, IL-6 and IL-1β have been linked to reduced insulin resistance, the suppression of these cytokines and potentiation of HO-adiponectin-ANP axis is important for enhanced glucose metabolism and improved kidney function observed in ZDFs." (PMID 24498225, 2014). "Chronic elevation of IL-6 levels in obese and type II diabetics may be associated with insulin resistance, while acute transient increase can enhance insulin sensitivity." (PMID 24563869, 2014). "Moreover, circulating IL-6 causes insulin resistance by increasing suppressor of cytokine signaling 3 expression in hepatocytes and mature adipocytes in vivo and in vitro." (PMID 23555753, 2013). "Thus, zonulin seems to be one of factors contributing to insulin resistance development; however, the association disappeared after adding plasma IL-6 level to the multiple regression analysis model." (PMID 23970898, 2013). "Increased plasma IL-6 concentrations are associated with insulin resistance." (PMID 23772224, 2013).
Insulin resistance (continued). "However, increased systemic concentrations of proinflammatory cytokines such as IL-6 are associated with systemic insulin resistance and the incidence of diabetes." (PMID 24023413, 2013). "Presumably, obesity and T2D-associated persistent systemic increases of IL-6 may trigger insulin resistance." (PMID 22272381, 2012). "IL-6 -174 (rs1800795) G allele carriers produce higher levels of IL-6 than those with the CC genotype, and have a higher prevalence of systemic juvenile-onset chronic arthritis, lipid abnormalities and insulin resistance." (PMID 22280494, 2012). "We hypothesized that reductions in adipose tissue mitochondrial content and/or respiration may explain, at least in part, the greater insulin resistance present in IL-6 deficient mice fed a HFD." (PMID 23240005, 2012). "The association of IL-6 and insulin resistance seems complex, and evidence suggests that IL-6 might act at multiple levels, both centrally and on peripheral tissues, to influence body weight, energy homeostasis, and insulin sensitivity." (PMID 22804097, 2012). "This investigation tests the hypothesis that expressions of TLR2 or TLR4 on monocytes and related inflammatory cytokines, such as TNF-α and IL-6, might be associated with insulin resistance in patients with RA." (PMID 23213270, 2012). "This hypothesis, while attractive, is difficult to reconcile with the long held view that IL-6, either directly, or working synergistically with other cytokines causes adipocyte and whole body insulin resistance." (PMID 23240005, 2012). "Also, we did not include other inflammatory markers, for example, TNF-α and TNF-modifying mediators in this study, thus we cannot exclude that some confounders related to both IL-6 and insulin resistance are affecting the associations we investigated." (PMID 22272193, 2012). "The hypothesized pathogenic role of IL-6 is largely based upon correlative data: T2DM is a chronic inflammatory state associated with both insulin resistance and elevated circulating levels of IL-6." (PMID 22962620, 2012). "Several studies have suggested, that IL-6 might be important in the development of insulin resistance and type 2 diabetes, however, a causal relationship in humans has not been proven so far." (PMID 21179199, 2010). "Moreover, visceral fat cells release some agents to the blood (e.g. plasminogen activator inhibitor-1, interleukin-6 and tumor necrosis factor-α) that are possibly linked to some aspects of insulin resistance." (PMID 20529329, 2010). "Interaction analysis for the inflammatory cytokine IL-6 revealed that stronger associations were observed in the subgroup with higher BMI, higher HbA1c value, and lower adiponectin levels, all markers associated with insulin resistance." (PMID 20525188, 2010). "Inhibition of IL-6 signalling improves insulin sensitivity in humans with immunological disease suggesting that elevated IL-6 levels in type 2 diabetic subjects might be causally involved in the pathogenesis of insulin resistance." (PMID 21179199, 2010). "Therefore, it would appear that low leptin concentrations, increased fat oxidation and insulin resistance are associated with increased concentrations of cortisol and interleukin-6 in weight-losing patients with pancreatic cancer." (PMID 15026790, 2004). "In addition, chronic stress triggers the release of pro-inflammatory cytokines, including interleukin-6 and tumor necrosis factor-alpha, which increase insulin resistance and cause chronic low-grade inflammation, contributing to oxidative stress and subsequent liver injury." (PMID 41196923, 2025). "In addition, several studies have demonstrated that sarcopenia was associated with insulin resistance, vitamin D deficiency, elevated levels of inflammatory cytokines (such as tumor necrosis factor-alpha and interleukin-6), and decreased concentrations of muscle factors (such as interleukin-15)." (PMID 38287345, 2024).
Insulin resistance (continued). "While some reported an association of IL-6 gene variants with insulin resistance and type 2 DM, other reported findings to the contrary, suggesting possible differences in the population characteristics that could contribute to the variations existing between studies." (PMID 38707766, 2024). "However, an increase in central obesity also influences muscle quality through insulin resistance and an increase in pro-inflammatory cytokines, such as tumor necrosis factor-alpha and interleukin-6, which are associated with lower muscle strength and physical function." (PMID 39184798, 2024). "In addition, TNFα may be associated with sarcopenia by promoting insulin resistance, delaying muscle repair, and exacerbating the pro-inflammatory response by up-regulating IL-6." (PMID 38732615, 2024). "IL-6 could be associated with hepatic insulin resistance, altered lipid metabolism, and SLD." (PMID 39766906, 2024). "Similarly, high IL-6 levels are associated with insulin resistance and disrupt glucose metabolism." (PMID 39840100, 2024). "Second, the DORADO project established IL-6 as the primary mediator of cytokines in post-pancreatitis diabetes, which exerts its glucose-regulating effects through insulin resistance (an increase in IL-6 by 1 ng/mL was associated with a 0.7% increase in insulin resistance (p = 0.038))." (PMID 36979645, 2023). "Therefore, IL-6 could be used as a surrogate marker of inflammation in obese children who are at risk for insulin resistance and metabolic syndrome." (PMID 36140983, 2022). "Among the three cytokines, IL-6 was the most likely mediator relating FM and insulin resistance at baseline; therefore, it could be used as a surrogate marker of inflammation in obese children who are at risk for insulin resistance and metabolic syndrome." (PMID 36140983, 2022). "In addition, IL-6 trans-signaling through the soluble IL-6 receptor (sIL-6R) had a major proinflammatory effect, with circulating sIL-6R more closely associated with insulin resistance status than waist-to-hip ratio or body mass index (BMI) in morbidly obese Taiwanese adults." (PMID 34504646, 2021). "Tumor necrosis factor α (TNF-α), resistin, and interleukin-6 (IL-6) were linked previously to insulin resistance, while adiponectin was found to enhance insulin sensitivity, increase glucose transepithelial transport, lower glucose synthesis in the liver, and suppress IL-6 and TNF-α." (PMID 35095801, 2021). "This is consistent with the rise in plasma TNFα and IL-6 emanating mostly from NF-κB activation in endothelial cells without involving adipokines released from adipose tissue macrophages that are typically associated with systemic insulin resistance and visceral obesity." (PMID 34440862, 2021). "Thus, rs180079 variant mediated increased IL6 expression may contribute to insulin resistance via TLR4 activation." (PMID 33820928, 2021). "In addition, cytokines (TNF-α, IL-6, and IL-1β) may play a role in the hepatic and systemic insulin resistance associated with NASH." (PMID 32316419, 2020). "Similarly, we found that baseline IL-6 and leptin levels were higher in participants with glycemic progression at the 10-year follow-up and that leptin level was significantly associated with higher glucose level, insulin resistance, and dyslipidemia." (PMID 31690939, 2020). "In addition to the positive associations of IL-6 and leptin with insulin resistance and secretion, NGF was higher in the GDM patients and strongly linked to glucose metabolism, insulin resistance and pancreatic β cell function in Chinese pregnant women in the second trimester." (PMID 33292292, 2020). "Moreover, ferritin as an inflammatory factor is connected with interleukin 6 and tumor necrosis factor alpha, which, in turn, may cause insulin resistance." (PMID 31969861, 2019).
Insulin resistance (continued). "Moreover, they suggest putative interactions between FGF23 and inflammatory regulatory pathways due to its association with comorbidities of psoriasis like insulin resistance, dyslipidemia, atherosclerosis, or markers of chronic inflammation like interleukin-6, CRP, TNFα, and fibrinogen." (PMID 31847236, 2019). "However, high levels of IL-6 have also been linked to insulin resistance." (PMID 31757005, 2019). "Finally, IL-6 has been implicated in the pathogenesis of insulin resistance." (PMID 29535681, 2018). "Indeed, inflammatory M1 macrophages infiltrating the obese WAT produce proinflammatory mediators (TNF-α, IL-1β, IL-6), which are associated with the development of insulin resistance and the subsequent release of NEFA, leading to systemic lipotoxicity, with effects on the liver and kidney." (PMID 28188334, 2017). "Also, an increase in the expression of IFN-γ and IL-6 was also associated with insulin resistance." (PMID 29234441, 2017). "It is well known that inflammatory cytokines TNFα and IL-6 could cause insulin resistance." (PMID 26938554, 2016). "However, it has been demonstrated that IL-6 administration causes hepatic insulin resistance." (PMID 24027356, 2013). "Moreover, AFs exposure may lead to significant reduction of leptin accompanied with high levels of cortisol, IL-6, and insulin resistance which together act to influence the feeding response, causing weight loss in patients with pancreatic cancer." (PMID 24959547, 2013). "Thus, in the present study, improvement of insulin resistance by the AI extract might be associated with decreased gene expression and/or production of cytokines such as TNFα, IL-6, MCP1, and leptin." (PMID 23401719, 2013). "However, it still remains unclear if these elevated IL-6 levels are co-incidental or if this cytokine is causally related to the development of insulin resistance and type 2 diabetes in humans." (PMID 21179199, 2010). "Interestingly, in these experiments, inhibition of IL-6 signalling in obese mice increased hepatic insulin sensitivity, suggesting that IL-6 in an obese organism might cause insulin resistance." (PMID 21179199, 2010). "Excess visceral adipose tissue is infiltrated by macrophages, which secrete TNF-α and IL-6, which serve to enhance insulin resistance by modulating the signaling of insulin through peripheral tissues, thus sustaining a pro-diabetogenic vicious circle." (PMID 41590667, 2026). "T2D similarly represents a chronic low‐grade inflammatory state, with TNF‐α and IL‐6 potentially driving worsening insulin resistance and β‐cell dysfunction." (PMID 41388732, 2026). "Alternatively, it suggests that IL-6′s contribution to insulin resistance is context-dependent, influenced by factors such as adiposity, hepatic function, and overall inflammatory burden." (PMID 40283677, 2025). "The IKK/NF-κB signaling pathway can be activated to increase the production of cytokines (e.g., TNF-α, IL-6, and IL-1β) to promote inflammation and insulin resistance." (PMID 40863244, 2025). "Obese adipose tissue releases exosomes rich in miR-155 that promote proinflammatory cytokine such as IL-6 and induce insulin resistance." (PMID 40696355, 2025). "This stimulates endothelial cells and immune components, triggering systemic cytokine rises (TNF-α, IL-1β, and IL-6), thereby contributing to atherosclerosis, insulin resistance, hypertension, and dyslipidemia." (PMID 41228440, 2025). "Functioning in the inflammatory response and cytokine activity, IL6 acts systemically from the extracellular space, regulating inflammation that contributes to insulin resistance in T2D and creates a pro-tumorigenic environment in cancers." (PMID 40127075, 2025). "Physical activity also stimulates muscle-derived IL-6 release, proportional to muscle mass and exercise intensity and decreases TNF-α levels and reduces insulin resistance risk." (PMID 41515940, 2025).
Insulin resistance (continued). "The production of inflammatory cytokines (such as TNF-α and IL-6) can induce insulin resistance and worsen the condition of diabetic patients." (PMID 41561166, 2025). "Integration of compound, target, and pathway data positioned IL-6 as a central mediator, interacting with MAPK1, MAPK3, MAPK14, PTGS2, and BCL2, genes associated with inflammation-induced insulin resistance and adipocyte dysfunction." (PMID 41382285, 2025). "Given the crucial role of hepatic inflammation in the development of insulin resistance, we examined the mRNA expression levels of two critical proinflammatory cytokines, IL-6 and TNF-α, using RT-qPCR." (PMID 39859525, 2025). "Thirteen overlapping targets between the gut microbiota and insulin resistance were identified, among which IL6, JUN, and PPARG were recognized as hub genes." (PMID 40625623, 2025). "The pro-inflammatory cytokines released in both conditions, such as TNF-α, IL-6, and IL-1β, impair insulin receptor signaling, leading to insulin resistance." (PMID 41007787, 2025). "In response, the body releases pro-inflammatory cytokines, notably interleukin-6 (IL-6) and tumor necrosis factor-alpha (TNF-α), which have been closely linked to insulin resistance and beta-cell dysfunction." (PMID 40742490, 2025). "Excess visceral fat secretes proinflammatory cytokines (TNF-α, IL-6) and adipokines (leptin), which promote oxidative stress and insulin resistance." (PMID 40702394, 2025). "VAT secretes pro-inflammatory adipokines (e.g., IL-6, TNF-α) that induce insulin resistance (a lung cancer risk factor and impair mitochondrial function." (PMID 41048699, 2025). "IL-6 contributes to insulin resistance through a complementary mechanism by activating the signal transducer and activator of transcription 3 (STAT3) pathway, which induces suppressor of cytokine signaling-3 (SOCS-3) expression." (PMID 41403736, 2025). "IL‐6 increases glucose oxidation and lipolysis, decreasing insulin resistance but can also lead to insulin resistance." (PMID 40243109, 2025). "Elevated temperatures trigger inflammatory cytokines like TNF-α and IL-6 in adipose tissue, which disrupt insulin signaling and contribute to insulin resistance." (PMID 41036090, 2025). "Chronic hyperglycemia and insulin resistance can amplify oxidative stress and promote the release of pro-inflammatory cytokines such as IL-6 and TNF-α, leading to sustained immune activation." (PMID 41476915, 2025). "IL-6 is a pleiotropic cytokine and affects different processes like vascular diseases, lipid metabolism, insulin resistance, mitochondrial activities and neuropsychological mechanisms." (PMID 40560328, 2025). "MPs activate pro‐inflammatory pathways, such as NF‐κB and MAPK, which lead to increased production of cytokines, such as IL‐6 and TNF‐α—factors implicated in insulin resistance as well as carcinogenesis." (PMID 41498107, 2025). "Levels of intrahepatic IL-6, a major proinflammatory cytokine, are increased in patients with MASLD, and sustained upregulation of IL-6 in rodent models is able to perpetuate hepatic insulin resistance." (PMID 40408301, 2025). "These cytokines include TNFα and interleukin-6 (IL-6), which have been considered to promote insulin resistance by inhibiting IRS activation by insulin receptor tyrosine kinase." (PMID 39873298, 2025). "Elevated levels of pro-inflammatory cytokines such as interleukin-6 (IL-6), C-reactive protein (CRP), and tumor necrosis factor-α (TNF-α) are associated with insulin resistance by interfering with insulin receptor signaling." (PMID 40137149, 2025). "The excess risk likely reflects multiple pathways: chronic inflammation (IL‐6 levels 30% higher in diabetics), endothelial dysfunction (flow‐mediated dilation reduced by 40%), and insulin resistance." (PMID 41383356, 2025).